ZNF25 (zinc finger protein 25)
Description:
Transcriptional repressor that plays a role in the proper differentiation of skeletal stem cells into osteoblasts.
Synonyms: KOX19; FLJ31890; Zfp9
Tractability: PROTAC: ubiquitination databases record sites on it.
Gene: Protein-coding gene on chromosome 10 (37,949,573 to 37,976,647, reverse strand). Ensembl gene ENSG00000175395.
Subcellular location: Nucleus
Subcellular location (Human Protein Atlas): Golgi apparatus; Nucleoplasm
Pathways (Reactome):
Gene expression (Transcription): Generic Transcription Pathway
Gene Ontology:
Molecular function: DNA-binding transcription repressor activity, RNA polymerase II-specific; protein binding; DNA-binding transcription factor activity, RNA polymerase II-specific; RNA polymerase II transcription regulatory region sequence-specific DNA binding
Biological process: osteoblast differentiation; regulation of transcription by RNA polymerase II; negative regulation of transcription by RNA polymerase II; regulation of DNA-templated transcription
Cellular component: nucleus
Genetic constraint (gnomAD): Loss-of-function variants: 23 observed, 37.78 expected, observed/expected ratio (o/e) 0.61, 90% interval 0.44 to 0.86. The upper end of that interval is the gene's LOEUF score, 0.86, which puts it in group 3 of 6, group 1 being the genes least tolerant of losing a copy. Missense variants: 501 observed, 551.2 expected, observed/expected ratio (o/e) 0.91, 90% interval 0.84 to 0.98. Synonymous variants: 169 observed, 190.51 expected, observed/expected ratio (o/e) 0.89, 90% interval 0.78 to 1.01.
Homologues: Orthologues: chimpanzee ZNF25 (99% identical), macaque ZNF25 (97% identical), pig ZNF25 (83% identical), rabbit ZNF25 (82% identical), guinea pig ZNF25 (81% identical), mouse Zfp9 (79% identical), rat Zfp9 (78% identical), Drosophila melanogaster CG3281 (31% identical), Drosophila melanogaster CG2712 (25% identical), Drosophila melanogaster Phs (24% identical). Paralogues in human: ZFP37 (50% identical), ZNF264 (48% identical), ZNF805 (48% identical), ZNF582 (47% identical), ZNF614 (47% identical), ZNF169 (47% identical), ZFP90 (46% identical), ZNF133 (46% identical), ZNF674 (46% identical), ZNF875 (46% identical), ZNF10 (46% identical), ZNF266 (46% identical), and 50 more.
Diseases named in the same sentence as ZNF25 in open-access papers:
ZNF25 is named in the same sentence as 6 diseases in open-access papers, as found by Europe PMC text mining. Sharing a sentence is not in itself a finding about the gene and the disease. The quoted sentences say what the papers report.
glioma (1 paper, 2026). A benign or malignant brain and spinal cord tumor that arises from glial cells (astrocytes, oligodendrocytes, ependymal cells). "This study provides new insights into the functional role of ZNF25 and highlights its potential as a therapeutic target, particularly in glioma." (PMID 42311244, 2026). "Functional assays demonstrated that ZNF25 knockdown suppressed the proliferation and migration of glioma cells." (PMID 42311244, 2026). "Based on these findings, functional validation was performed in glioma cell lines (U87-MG and A172) via siRNA-mediated knockdown of ZNF25, followed by cell viability assays, wound healing assays, and Western blot assays." (PMID 42311244, 2026).
osteoarthritis (1 paper, 2025). A noninflammatory degenerative joint disease occurring chiefly in older persons, characterized by degeneration of the articular cartilage, hypertrophy of bone at the margins and changes in the synovial membrane. "Specifically, ZNF25 was suggested as a candidate gene for osteoblast differentiation in humans, KLHL14 as a candidate gene for bone strength in chicken, and ATP9B as a candidate gene regulating the progression of osteoarthritis." (PMID 40965274, 2025).
ZNF25 also shares sentences with these, for which no sentence is quoted: cancer (1 paper); endometriosis (1); genetic diseases (1); ovarian carcinoma (1).